MIR4661 (microRNA 4661)
Synonyms: hsa-mir-4661
Gene: MicroRNA gene on chromosome 8 (91,205,485 to 91,205,559, forward strand). Ensembl gene ENSG00000266194.
Homologues: Orthologues: chimpanzee MIR4661 (100% identical).